ATG4B (autophagy related 4B cysteine peptidase)
Description:
Cysteine protease that plays a key role in autophagy by mediating both proteolytic activation and delipidation of ATG8 family proteins. Required for canonical autophagy (macroautophagy), non-canonical autophagy as well as for mitophagy. The protease activity is required for proteolytic activation of ATG8 family proteins: cleaves the C-terminal amino acid of ATG8 proteins MAP1LC3A, MAP1LC3B, MAP1LC3C, GABARAPL1, GABARAPL2 and GABARAP, to reveal a C-terminal glycine. Exposure of the glycine at the C-terminus is essential for ATG8 proteins conjugation to phosphatidylethanolamine (PE) and insertion to membranes, which is necessary for autophagy. Protease activity is also required to counteract formation of high-molecular weight conjugates of ATG8 proteins (ATG8ylation): acts as a deubiquitinating-like enzyme that removes ATG8 conjugated to other proteins, such as ATG3. In addition to the protease activity, also mediates delipidation of ATG8 family proteins. Catalyzes delipidation of PE-conjugated forms of ATG8 proteins during macroautophagy. Also involved in non-canonical autophagy, a parallel pathway involving conjugation of ATG8 proteins to single membranes at endolysosomal compartments, by catalyzing delipidation of ATG8 proteins conjugated to phosphatidylserine (PS). Compared to other members of the family (ATG4A, ATG4C or ATG4C), constitutes the major protein for proteolytic activation of ATG8 proteins, while it displays weaker delipidation activity than other ATG4 paralogs. Involved in phagophore growth during mitophagy independently of its protease activity and of ATG8 proteins: acts by regulating ATG9A trafficking to mitochondria and promoting phagophore-endoplasmic reticulum contacts during the lipid transfer phase of mitophagy.
Synonyms: HsAPG4B; APG4B; AUTL1; KIAA0943; DKFZp586D1822
Tractability: Small molecule: a high-quality ligand is known; it belongs to a druggable protein family. PROTAC: UniProt records ubiquitination sites on it; ubiquitination databases record sites on it; its protein half-life has been measured; a small molecule that binds it is known.
Target class: Enzyme
Gene: Protein-coding gene on chromosome 2 (241,637,213 to 241,673,857, forward strand). Ensembl gene ENSG00000168397.
Subcellular location: Cytoplasm; Cytoplasm, cytosol; Cytoplasmic vesicle, autophagosome; Endoplasmic reticulum; Mitochondrion
Subcellular location (Human Protein Atlas): Cytosol; Nucleoplasm
Pathways (Reactome):
Autophagy: Macroautophagy
Gene Ontology:
Molecular function: cysteine-type endopeptidase activity; cysteine-type peptidase activity; endopeptidase activity; protein binding; protein-phosphatidylethanolamide deconjugating activity; scaffold protein binding
Biological process: autophagosome assembly; autophagy; microautophagy; mitophagy; protein delipidation; protein localization to phagophore assembly site; proteolysis; aggrephagy; macroautophagy; otolith mineralization completed early in development; piecemeal microautophagy of the nucleus; protein processing
Cellular component: autophagosome membrane; cytoplasm; endoplasmic reticulum; mitochondrion; cytosol; autophagosome
Genetic constraint (gnomAD): Loss-of-function variants: 29 observed, 46.48 expected, observed/expected ratio (o/e) 0.62, 90% interval 0.46 to 0.85. The upper end of that interval is the gene's LOEUF score, 0.85, which puts it in group 3 of 6, group 1 being the genes least tolerant of losing a copy. Missense variants: 461 observed, 475.61 expected, observed/expected ratio (o/e) 0.97, 90% interval 0.9 to 1.05. Synonymous variants: 224 observed, 186.53 expected, observed/expected ratio (o/e) 1.2, 90% interval 1.08 to 1.34.
Homologues: Orthologues: chimpanzee ATG4B (99% identical), guinea pig ATG4B (95% identical), dog ATG4B (95% identical), mouse Atg4b (95% identical), rat Atg4b (94% identical), macaque ATG4B (94% identical), pig ATG4B (92% identical), rabbit ATG4B (92% identical), tropical clawed frog atg4b (75% identical), zebrafish atg4b (74% identical), Drosophila melanogaster Atg4a (44% identical), Caenorhabditis elegans atg-4.1 (40% identical). Paralogues in human: ATG4A (54% identical), ATG4D (34% identical), ATG4C (30% identical).
Diseases named in the same sentence as ATG4B in open-access papers:
ATG4B is named in the same sentence as 76 diseases in open-access papers, as found by Europe PMC text mining. Sharing a sentence is not in itself a finding about the gene and the disease. The quoted sentences say what the papers report.
colorectal cancer (19 papers, 2016 to 2025). A primary or metastatic malignant neoplasm that affects the colon or rectum. "Through experimental studies, they found that circATG4B promoted autophagy in colorectal cancer cells by encoding a novel protein, ATG4B‐222aa, which increased the resistance of colorectal cancer cells to oxaliplatin." (PMID 37070530, 2023). "ATG4B has been implicated in several cancers, such as colorectal cancer (CRC), gastric carcinoma, and breast Cancer." (PMID 36539845, 2022). "This compound, named as S130, inhibited the autophagy flux and arrested the growth of colorectal xenograft models, this study advanced our knowledge of the association of ATG4B and colorectal cancers." (PMID 31083460, 2019). "ATG4B overexpression is associated with cancer development in patients with colorectal cancer and chronic myeloid lymphoma (CML)." (PMID 31771238, 2019). "Conversely, silencing NEAT1 reduces autophagy by influencing ATG9A and ATG4B, which increases sensitivity to 5-fluorouracil in colorectal cancer." (PMID 39715205, 2024). "ATG4B expression is highly elevated in human epidermal growth factor receptor 2-positive breast cancer and colorectal cancer." (PMID 37370041, 2023). "Pharmacological and genetic inhibition of ATG4B inhibited colorectal cancer cell proliferation and xenograft tumor growth." (PMID 35184132, 2022). "Accumulating studies suggest that ATG4B plays oncogenic roles in a number of cancers, such as colorectal cancer and glioblastoma (GBM)." (PMID 35184132, 2022). "This also did reveal that the Ebselen was indeed working through ATG4B to suppress the growth of relevant colorectal cancer cell lines." (PMID 36539845, 2022). "Cysteine protease ATG4B, a key autophagy protein, is an attractive target for colorectal cancer therapy." (PMID 36539845, 2022). "We have previously shown that compound UAMC-2526, a low micromolar ATG4B inhibitor, inhibits tumor growth in a mouse HT-29 tumor xenograft model of human colorectal cancer by inhibiting ATG4B." (PMID 34868951, 2021). "Recently, two lncRNAs have been reported to promote autophagy and chemoresistance in colorectal cancer through miR-34a/ATG4B pathway." (PMID 34409031, 2021). "It has been reported that ATG4B can promote the growth of colorectal cancer, while silencing the expression of ATG4B can reduce the colony formation of cancer cells and inhibit tumor growth." (PMID 33604190, 2021). "We have previously shown that compound UAMC-2526 inhibits tumor growth in a mouse HT-29 tumor xenograft model of human colorectal cancer by inhibiting cysteine protease ATG4B." (PMID 34868951, 2021). "The current study findings indicate that the dual effect inhibitor 163N offers an attractive new anti-cancer drug and compounds having a combination of lysosome inhibition and ATG4B inhibition are a promising therapeutic strategy for colorectal cancer therapy." (PMID 32532053, 2020). "A previous study has shown that high ATG4B expression intensity was almost correlated with late tumor stages (II-IV) of colorectal cancer patients." (PMID 32532053, 2020). "ATG4B is highly expressed in tumor tissues, compared to the expression in normal cells, in different types of cancer, such as colorectal cancer, CML, and breast cancer." (PMID 31159487, 2019). "These ATG4B inhibitors can suppress colorectal cancer cell growth and synergize the killing effect of cancer cells with autophagy-induction." (PMID 31771238, 2019). "Some ATG4B inhibitors identified to date have been tested in xenograft models of colorectal cancer cells, typically HCT-116 cells, and demonstrated a significant benefit in reducing tumour growth, in particular when combined with chemotherapeutic agents." (PMID 31878323, 2019). "Overall, there is clear evidence that targeting ATG4B can provide a benefit in cancer, and there is particularly good evidence for breast cancer, lung cancer, colorectal cancer, and pancreatic ductal adenocarcinoma." (PMID 31878323, 2019).
colorectal cancer (continued). "Silencing ATG4B decreases tumor growth of colorectal cancer and cancer stemness of cluster of differentiation 34(CD34+) CML." (PMID 31771238, 2019). "Inactivation or silencing of ATG4B also decreased the cell viability in various cancer cells, including hepatoma cells, breast cancer cells, glioma, and colorectal cancer cells." (PMID 31159487, 2019). "ATG4B expression was found elevated in colorectal cancer, and knockdown of ATG4B resulted in reduced cell cycle progression and inhibition of colorectal cancer cell lines." (PMID 31878323, 2019). "ATG4B expression in tumor tissues is much higher than that in adjacent normal cells of colorectal cancer patients." (PMID 31159487, 2019). "ATG4B is a cytosolic cysteine protease required for autophagy machinery, and it is elevated in several types of cancer, particularly colorectal cancer." (PMID 31159487, 2019). "However, little is known about the relationship of ATG4B and its phosphorylated form at Ser 383 and 392 sites (pS383/392-ATG4B), with clinical outcomes, particularly in colorectal cancer (CRC)." (PMID 37038218, 2023). "Recent studies have demonstrated that using small molecule inhibitors of ATG4B could suppress the growth of colorectal cancer cells, or sensitize colorectal cancer cells to chemotherapy." (PMID 32532053, 2020). "Our current results showed that X. strumarium and T. terrestris extracts could inhibit ATG4B and reduce the cell viability of colorectal cancer cells." (PMID 31159487, 2019). "Our study suggested that X. strumarium fruit might contain active ingredients to inhibit colorectal cancer cells through ATG4B suppression." (PMID 31159487, 2019). "Taken together, the results showed that the fruit of X. strumarium may have an active ingredient to inhibit ATG4B and suppress the proliferation and metastatic characteristics of colorectal cancer cells." (PMID 31159487, 2019). "Moreover, in the occurrence and development in grades of colorectal cancer, high expression of ATG4B also appeared in grade 1, grade 2 and grade 3, which might be responsible for tumor deterioration." (PMID 36539845, 2022). "Moreover, the extracts from X. strumarium diminished the migration and invasion of colorectal cancer cells, suggesting the ingredients of X. strumarium may inhibit ATG4B and have anti-cancer effects in colorectal cancer cells." (PMID 31159487, 2019). "In addition, silencing ATG4B increases autophagic flux in colorectal cancer cells." (PMID 27632526, 2016). "The colorectal cancer data in the TCGA database were abstracted to investigate the relationship between COAD and ATG4B expression." (PMID 36539845, 2022). "S130 acts as an inhibitor of ATG4B, reacting on the early stage of autophagy via reducing splicing of LC3 by ATG4B in colorectal cancer." (PMID 34823534, 2021). "Reportedly, ATG4B was a potential therapeutic target for colorectal cancer (CRC, COAD), although not fully elucidated." (PMID 36539845, 2022). "ATG4B has been reported as an oncogene in various cancer cells, including osteosarcoma, chronic myeloid leukemia (CML), human epidermal growth factor receptor 2 (HER2)-positive breast, and colorectal cancer cells." (PMID 32532053, 2020). "Indeed, silencing ATG4B elevates autophagic flux in colorectal cancer cells, which implies that excessive ATG4B has negative effects on autophagy." (PMID 30870514, 2019). "One study has shown that the growth arrest induced by knockdown of ATG4B in human colorectal cancer cells was independent of the autophagic flux, suggesting that ATG4B could have additional functions independent of autophagy." (PMID 31083460, 2019). "A similar decrease in cell viability and proliferation under starvation following ATG4B inhibition was observed in osteosarcoma and colorectal cancer cells; however, in the colorectal cancer model, the growth arrest induced by silencing ATG4B was independent of autophagic flux." (PMID 27556700, 2016).
colorectal cancer (continued). "Together, 163N might exert its antitumor effect through targeting autophagy, and only deletion of ATG4B is not sufficient to suppress tumor growth, which may explain why the dual functional autophagy inhibitor 163N can potently inhibited the growth of colorectal cancer cells." (PMID 32532053, 2020). "For example, tumor cells of colorectal cancer patients had significantly higher ATG4B expression level than adjacent normal cells, suggesting that ATG4B plays a positive role in colorectal cancer development although the enhancement for cell proliferation by ATG4B is independent of autophagy." (PMID 31083460, 2019). "A previous study showed that ATG4B knockdown increased CCND1 expression and resulted in colorectal cancer cell growth arrest independent of autophagy." (PMID 35184132, 2022).
breast carcinoma (18 papers, 2015 to 2026). "Together, these findings support a positive association between HER2 and ATG4B protein levels in breast cancer." (PMID 27556700, 2016). "In this study, we pursued the in vitro and in vivo evaluation of this novel association and analyzed the context-dependent roles that ATG4B plays in breast cancer cells." (PMID 27556700, 2016). "Together these results demonstrate a novel association of ATG4B positive expression with HER2 positive breast cancers and indicate that this subtype is suitable for emerging ATG4B inhibition strategies." (PMID 27556700, 2016). "The ATG4B is an important factor in the chemotherapy resistance of lung cancer, breast cancer and prostate cancer." (PMID 35193115, 2022). "ATG4B expression is highly elevated in human epidermal growth factor receptor 2 (HER2)-positive breast cancer." (PMID 31878323, 2019). "On the other hand, suppression of ATG4B using a dominant negative version resulted in increased cell migration and potential for increased lung metastases in a model of hypoxic breast cancer cells." (PMID 31878323, 2019). "Further, siRNA-mediated knockdown of ATG4B and HER2 resulted in a decrease of breast cancer cell viability, and a combination of ATG4B knockdown with the HER2 inhibitor trastuzumab resulted in a strong reduction of cell viability in HER2-overexpressing cells." (PMID 31878323, 2019). "One hundred of the predicted best binding ATG4B inhibitors were obtained to test for effects on GFP-LC3B puncta levels in SKBR3-hrGFP-LC3B breast cancer cells cultured in standard fed conditions." (PMID 30076329, 2018). "In breast cancer, one study reported that ATG4B inhibited growth of triple-negative breast cancer cell lines and a candidate agonist of ATG4B, Flubendazole, displayed anti-proliferative effects." (PMID 30076329, 2018). "Another study identified an association between HER2 and ATG4B and showed that HER2 positive breast cancer cells are sensitive to ATG4B inhibition under stress conditions." (PMID 30076329, 2018). "In this study, we investigated the expression of ATG4B in breast cancer, a heterogeneous disease comprised of several molecular subtypes." (PMID 27556700, 2016). "In conclusion, we showed, for the first time, a functional association between ATG4B and HER2 in breast cancer cells." (PMID 27556700, 2016). "Treatment with trastuzumab (Herceptin) in combination with ATG4B siRNA-mediated knockdown in Herceptin-sensitive and -resistant breast cancer cells significantly reduced cell viability compared to trastuzumab alone in all tested cell lines." (PMID 27556700, 2016). "Our study is the first to show ATG4B inhibition as a strategy to sensitize HER2 positive breast cancer cells to anti-HER2 therapy (trastuzumab)." (PMID 27556700, 2016). "Taken together, these findings indicate that ATG4B inhibition can be an effective strategy to sensitize HER2-positive breast cancer cells to anti-HER2 therapy." (PMID 27556700, 2016). "In addition, previous studies have shown that ErbB2 can block autophagy initiation by modulation of Beclin 1 in breast cancer and Alzheimer’s disease, and regulate autophagic cell death by modulation of ATG4B expression in retinal pigment epithelium cells." (PMID 33854045, 2021). "Thus, in the case of breast cancer, evidence suggests that modulation of ATG4B provides a benefit in pre-clinical models." (PMID 31878323, 2019). "A role for ATG4B in cancer has been proposed, including chronic myeloid leukemia, osteosarcoma, colorectal cancer, prostate cancer, breast cancer and pancreatic adenocarcinoma." (PMID 30443548, 2018). "We examined a panel of breast cancer cell lines, xenograft tumors, and breast cancer patient specimens for the protein expression of ATG4B, and found a positive association between HER2 and ATG4B protein expression." (PMID 27556700, 2016). "Importantly, we showed that ATG4B inhibition sensitized HER2-positive breast cancer cells to anti-HER2 treatment." (PMID 27556700, 2016).